TRPS1 (transcriptional repressor GATA binding 1)
Diseases named in the same sentence as TRPS1 in open-access papers (continued):
Sharing a sentence is not in itself a finding about the gene and the disease.
trichorhinophalangeal syndrome (19 papers, 2010 to 2025). "We report a case of trichorhinophalangeal syndrome and analyze the TRPS1 gene mutation in the patient's family." (PMID 40756095, 2025). "Trichorhinophalangeal syndrome (TRPS) is a rare autosomal dominant genetic disorder caused by mutations in the TRPS1 gene and is characterized by craniofacial abnormalities and skeletal deformities." (PMID 40756095, 2025). "Trps1, a transcription factor associated with the skeletal defects of Trichorhinophalangeal Syndrome, was also down-regulated in mutant IVD." (PMID 20214815, 2010). "Mutations in the Trps1 gene lead to the human condition tricho‐rhino‐phalangeal syndrome which is characterised by craniofacial and skeletal dysplasias and siRNA mediated knockdown of Trps1 in a pre‐odontoblastic cell line leads to the suppression of Phospho1, Alpl and Smpd3 expression." (PMID 36540015, 2023). "The name of this protein and the gene come from the trichorhinophalangeal syndrome (TRPS), a rare autosomal-dominant skeletal dysplasia caused by mutations in the TRPS1 gene." (PMID 35573139, 2022). "Trichorhinophalangeal syndrome (TRPS) is an autosomal dominant disorder resulting from heterozygous mutations of the TRPS1 gene." (PMID 31130868, 2019). "Trichorhinophalangeal syndrome (TRPS) is a rare autosomal dominant disorder caused by defects involving the TRPS1 gene." (PMID 30458885, 2018). "Trichorhinophalangeal syndrome is characterized by scarce scalp hair in association with other abnormalities; mutations in zinc finger transcription factor Trps1 is considered to be the cause of this disorder since Trps1 is considered essential for normal HF development." (PMID 24451143, 2014). "Trichorhinophalangeal syndrome (TRPS) is a rare skeletal dysplasia of autosomal dominant inheritance, caused by a defect in the TRPS1 gene." (PMID 23691375, 2013). "The TRPS1 and IL6ST genes are associated with trichorhinophalangeal syndrome (OMIM #190350) and Stuve-Wiedemann syndrome (OMIM #619751) in autosomal dominant and recessive modes, respectively." (PMID 39989454, 2025). "Cleft palate has been reported in rare cases of the trichorhinophalangeal syndrome (TRPS), an autosomal dominant disorder resulting from mutations in the TRPS1 gene, which encodes the transcriptional repressor TRPS1." (PMID 31130868, 2019). "Trichorhinophalangeal syndrome is a skeletal dysplasia with skeletal defects as well as dental abnormalities, where Trps1 gene regulates dental mineralization." (PMID 31569682, 2019). "Defects in TRPS1 lead to trichorhinophalangeal syndrome, a genetic syndrome characterized by coarse facies, brittle hair and skeletal defects." (PMID 27424798, 2016). "The company report also flagged rare heterozygous variants in NF1 and TRPS1, which would, if truly present and functional, cause autosomal dominant disorders (neurofibromatosis (OMIM #162200) and trichorhinophalangeal syndrome (OMIM # 190350), respectively)." (PMID 24954083, 2014). "Our TRPS1 variants were not located in the mutation hotspots causing trichorhinophalangeal syndrome, such as the GATA-type Zn finger domain (894–952 residues)." (PMID 39989454, 2025). "Trps1 was reported to play a role in regulating genes that control the growth of bone and other skeletal tissues, and the aberrant expression of the human homolog of TRPS1 leads to trichorhinophalangeal syndrome." (PMID 37255601, 2023). "However, a gender difference of tooth formation has been reported using Trps1+/− (trichorhinophalangeal syndrome heterozygous) mice showing significantly smaller crown and root volumes in female Trps1+/− mice compared with male Trps1+/− mice." (PMID 31569682, 2019). "For example, she had no cutaneous tumors or facial features of trichorhinophalangeal syndrome, so the rare variants reported in NF1 and TRPS1 were likely benign variants or possibly false positives." (PMID 24954083, 2014).
breast tumors (15 papers, 2010 to 2025). "For example, TRPS1 is frequently amplified in breast tumors, and this amplification is associated with worse prognosis." (PMID 38377146, 2024). "Altogether, these data indicate that TRPS1 and Cath-D are implicated in luminal breast tumor oncogenesis by promoting cell cycle progression and maintaining the transformed phenotype in ER+ BCC." (PMID 26183398, 2015). "Apart from breast, a broader immunoreactivity of TRPS1 was observed in non-breast tumors, including lung, Mullerian, and bladder cancers in our cohort." (PMID 40025593, 2025). "As with many developmentally important genes co-opted during the process of cancer initiation and progression, TRPS1 is commonly over-expressed in breast tumors, both relative to normal tissue and relative to other tumor types." (PMID 38377146, 2024). "Limited data exist regarding TRPS1 positivity in other primary breast neoplasms." (PMID 38902365, 2025). "Although it was initially reported as a highly sensitive and specific marker of epithelial and mesenchymal neoplasms of the breast, more recent data have shown that TRPS1 is expressed by various other non-breast neoplasms, including benign and malignant cutaneous ones." (PMID 39449380, 2024). "TRPS1 is a repressive GATA-family TF that is overexpressed in breast tumors." (PMID 37461612, 2023). "GATA3 is positively associated with ESR1, while TRPS1 is correlated with ERBB2 and might act as a potential modulator of chemosensitivity in breast tumor." (PMID 28423734, 2017). "Moreover, a slight upregulation of the oncogene c-Myc, along with an undetectable level of breast tumor-related gene Bag-1 and TRPS-1, was observed in BME65Cs cells while these genes are all highly expressed in MCF-7." (PMID 20969773, 2010). "Thus, TRPS1 is commonly overexpressed in human breast tumours, is anti-correlated with YAP activity and 4T1 cells critically depend on high Trps1 expression to efficiently establish tumour formation in vivo, possibly due to TRPS1’s effect on immunosurveillance." (PMID 30082728, 2018). "Another limitation of our study was that when TRPS1 positivity was noted in a metastatic sample, concurrent TRPS1 testing was not performed on the primary breast tumor sample." (PMID 40025593, 2025). "We then investigated Cath-D and TRPS1 expression in ER+/ER− BCC lines and breast tumor samples." (PMID 26183398, 2015). "A potential pitfall emerges with high-grade breast tumors exhibiting a solid growing pattern, as TRPS1 alone may not effectively distinguish between undifferentiated breast carcinoma and AS." (PMID 38902365, 2025).
prostate carcinoma (14 papers, 2004 to 2025). A carcinoma that arises from epithelial cells of the prostate gland. "Although TRPS1 was previously linked to apoptosis of prostate cancer cells and chondrocytes, we found that TRPS1 silencing had little effect on BT474 cell apoptosis." (PMID 25277197, 2014). "TRPS1 was found to be highly expressed in androgen-dependent prostate cancer (LNCaP-FGC) cells compared with androgen-independent prostate cancer (LNCaP-LNO) cells." (PMID 41210689, 2025). "On the other hand, over expression of the TRPS1 gene by transiently transfecting TRPS1-encoding vectors leads to a dramatic increase in the apoptotic index of both COS-1 cells and LNCaP prostate cancer cells." (PMID 24709795, 2013). "TRPS1 was recently found to be more expressed in androgen-dependent than androgen-independent LNCaP prostate cancer cell lines by differential display analysis." (PMID 14997205, 2004). "In conclusion, the results indicate that overexpression of MYC and TRPS1 are rare in prostate cancer in vivo." (PMID 14997205, 2004). "The expression of TRPS1 in urothelial and prostate carcinoma remains inadequately elucidated." (PMID 38902365, 2025). "TRPS1 may participate in oxidative stress-induced apoptosis in androgen-independent DU145 prostate cancer cells." (PMID 38778150, 2024). "For example, human prostate cancer studies demonstrated that TRPS1 is repressed by androgens." (PMID 35573139, 2022). "Before Trps1 was assigned to be the causative gene whose mutation leads to tricho-rhino-phalangeal syndrome, GC79 (the previous name for TRPS1) was found to be one of the differentially expressed genes between androgen-dependent and independent prostate cancers." (PMID 24709795, 2013). "In 2004, the same group found that TRPS1 protein expression was downregulated by androgens in human prostate cancer, and analysis of TRPS1 mRNA expression levels in several human tissues showed that the highest levels were observed in normal and cancerous breast tissues." (PMID 23762846, 2013). "In order to evaluate the significance of EIF3S3, MYC, and TRPS1 in breast and prostate cancer, we have analysed the expression and copy number of the three genes in cell lines and tumours using quantitative real-time RT–PCR and fluorescence in situ hybridisation (FISH)." (PMID 14997205, 2004). "However, only 24.6% of all prostate carcinomas show an intermediate to high expression of TRPS1." (PMID 39518009, 2024). "NKX2-5, RUNX1, TRPS1, FOXO1, and TP63 play a inhibitory roles in the development of prostate cancer." (PMID 38778150, 2024). "The transcriptional activities of NKX2-5, RUNX1, TRPS1, FOXO1, and TP63 are negatively correlated with LEGs, suggesting these suppress prostate cancer lineage plasticity through the RTK/RAS pathway." (PMID 38778150, 2024). "TRPS1 was first discovered as one of the differentially expressed genes between androgen-dependent (LNCaP-FGC) and androgen-independent (LNCaP-LNO) prostate cancer cell lines." (PMID 24709795, 2013). "Next, breast and prostate cancer cell lines were analysed for copy numbers of the EIF3S3, MYC and TRPS1 genes." (PMID 14997205, 2004). "The TRPS1 and MYC expression levels were similar in all prostate tumour groups, whereas EIF3S3 expression was higher (P=0.029) in prostate carcinomas compared to BPH." (PMID 14997205, 2004). "TRPS1 is androgen-repressible in androgen-dependent, but not in androgen-independent, prostate cancers." (PMID 24709795, 2013). "After that, they also demonstrated that the overexpression of TRPS1 protein was correlated with reduced protein expression of certain antioxidants, suggesting a possible involvement of TRPS1 in oxidative stress and possibly in apoptosis in androgen-independent DU145 prostate cancer cells." (PMID 23762846, 2013).
prostate carcinoma (continued). "TRPS1 has begun to attract wide attention as an important regulator of apoptosis, as it has been found that TRPS1 protein expression is androgen-suppressive in androgen-dependent (LNCaP-FGC) prostate cancer cells but not in androgen-independent (LNCaP-LNO) prostate cancer cells." (PMID 24709795, 2013).
trichorhinophalangeal syndrome type I (11 papers, 2010 to 2024). An autosomal dominant malformation syndrome caused by mutations in TRPS1 characterized by distinctive craniofacial and skeletal abnormalities. "The TRPS1 gene, known as trichorhinophalangeal syndrome type 1, is associated with hir-sutism in both humans, specifically Ambras syndrome (AS), and the koala phenotype in mice." (PMID 39308831, 2024). "Trichorhinophalangeal syndrome, type I (OMIM: #190350) is caused by haploinsuffiency in the transcription factor Trps1." (PMID 20214815, 2010). "Previous studies show that miR-222-3p has an oncogenic effect by regulating MMP2 (matrix metalloproteinaza), MMP9, TRPS1 (trichorhinophalangeal syndrome type 1), and CDKN1C/p57 (cyclin-dependent kinase inhibitor 1C)." (PMID 38542261, 2024). "Trichorhinophalangeal syndrome type 1 (TRPS1) is named for a very rare hereditary disease with mainly autosomal dominant inheritance features characterized by craniofacial and skeletal abnormalities with damage and mutation affecting chromosome 8q." (PMID 36284362, 2022). "Trichorhinophalangeal syndrome type I (TRPS I; MIM 190350) is a rare autosomal dominant disorder of congenital malformations due to variants of the gene TRPS1." (PMID 36291383, 2022). "It has previously been demonstrated that miR-221/222 down-regulate E-cadherin through targeting of the 3′UTR of TRPS1 (trichorhinophalangeal syndrome type 1), a transcriptional repressor that inhibits EMT through repressing ZEB2." (PMID 30591655, 2018). "By searching those transcripts with PGMapper, we found one important candidate gene: zinc finger transcription factor for trichorhinophalangeal syndrome type I protein (Trps1)." (PMID 24416236, 2014). "One FGFR3 mutation (c.1620C>A p.N540K), one likely pathogenic GNAS mutation (c.2288C>T p.A763V), and one TRPS1 mutation (c.2527_c.2528dupTA p.S843fsX72) was identified in three pedigrees with hypochondroplasia, pseudohypoparathyroidism Ia (PHP-Ia), and trichorhinophalangeal syndrome type I (TRPS I)." (PMID 34740356, 2021).
triple-negative breast carcinoma (11 papers, 2014 to 2025). An invasive breast carcinoma which is negative for expression of estrogen receptor (ER), progesterone receptor (PR), and human epidermal growth factor receptor 2 (HER2). "They found that while the positive expression rate of TRPS1 in TNBC (triple-negative breast cancer) was nearly 90%, weaker expression was also observed in 71% of endometrial cancers." (PMID 40822238, 2025). "In recent years, TRPS1 has been reported as a breast marker with satisfactory sensitivity and specificity in triple-negative breast cancers (TNBC)." (PMID 40822238, 2025). "TRPS1, by comparison, has shown more consistent expression across both luminal and triple-negative breast cancers, with a higher sensitivity reported in some studies, particularly in challenging TNBC cases." (PMID 39518009, 2024). "RNA-seq analysis of the HCC3153 and SUM159 triple-negative breast cancer cell lines identified 925 and 664 common up- and downregulated genes (adjusted p < 0.05) after TRPS1 knockdown." (PMID 33548228, 2021). "Background/Objectives: Immunohistochemical expression of TRPS1 (trichorhinophalangeal syndrome type 1) protein is usually used by pathologists to confirm breast origin for triple-negative breast cancers (TNBC) or metastatic carcinomas of unknown primary." (PMID 39518009, 2024). "Furthermore, reduced metastatic spread of triple negative breast cancer cells by TRPS1 has also been described." (PMID 30071870, 2018). "Studies have shown that the positive rate of TRPS1 in ER-positive breast cancer is 98%, similar to GATA3 (96%), while the positive rate in triple-negative breast cancer (TNBC) is 86%, significantly higher than GATA3 (45%)." (PMID 40822238, 2025). "TRPS1 was also found to be positively related with IMP3, which is expressed preferentially in triple negative breast cancers (TNBC)." (PMID 24934762, 2014).
osteosarcoma (8 papers, 2015 to 2024). A usually aggressive malignant bone-forming mesenchymal neoplasm, predominantly affecting adolescents and young adults. "In our study, we first reported that high TRPS1 transcription predicted better survival in a subset of patients who have received chemotherapy, which was supported by a recent study showing that TRPS1 was associated with the multidrug resistance of osteosarcoma by regulating MDR1 gene expression." (PMID 28423734, 2017). "More interestingly, the expression of several of these genes, including CHST13, FKBP11, SGMS2, TRPS1, PRKX, SP7, and DNAJC1, were highly associated with osteosarcoma prognosis." (PMID 37457661, 2023). "The risk heat map showed that the gene expression of ST3GAL4, TRIM8, STC2, TRPS1, and FAM207A increased from low-risk to high-risk groups, indicating that the five genes in this study were related to osteosarcoma." (PMID 35102149, 2022). "ST3GAL4, TRIM8, STC2, TRPS1, and FAM207A are high-risk genes that are involved in the occurrence and development of osteosarcoma." (PMID 35102149, 2022). "Our results showed that TRPS1 was negatively correlated with monocytes in osteosarcoma (R = –0.24)." (PMID 35102149, 2022). "Hence, this current study was designed to explore Trps1 expression and evaluate its significance to intratumoural microvessels density in osteosarcoma." (PMID 26377811, 2015). "Trps1 plays a crucial role in osteosarcoma angiogenesis, metastasis and clinical surgical stage." (PMID 26377811, 2015). "The study indicated that Trps1 may have a clinical potential not only as a promising prognostic marker, but also as a novel therapeutic target in anti-angiogenesis for osteosarcoma." (PMID 26377811, 2015). "Trps1 can be a novel promising prognostic marker and therapeutic target, and antiangiogenic therapy which targets Trps1 molecule in patients with osteosarcoma may lead to improved prognosis and longer-term survival." (PMID 26377811, 2015). "This expression is probably related to the upregulation of TRPS1 and YAP1 in osteosarcoma cell lines with circTADA2A, enhancing their expression and leading to increased cell proliferation and drug resistance." (PMID 39518009, 2024). "The results showed that the expression levels of ST3GAL4, TRIM8, STC2, TRPS1, and FAM207A genes were significantly higher in the osteosarcoma cell line compared to that in the normal human osteoblasts." (PMID 35102149, 2022). "We performed qRT-PCR to detect the expression of ST3GAL4, TRIM8, STC2, TRPS1, and FAM207A genes in normal human osteoblasts (hFOB1.19) and osteosarcoma cells (MG63 and SJSA-1)." (PMID 35102149, 2022). "Our findings suggested that ST3GAL4, TRIM8, STC2, TRPS1, and FAM207A could be used as potential biomarkers for the prognosis of patients with osteosarcoma." (PMID 35102149, 2022).